PTBP1 (polypyrimidine tract binding protein 1)
Diseases named in the same sentence as PTBP1 in open-access papers (continued):
Sharing a sentence is not in itself a finding about the gene and the disease.
glioblastoma (37 papers, 2011 to 2026). The most malignant astrocytic tumor (WHO grade IV). "PTBP1 was closely related to patients' age, glioblastoma grade, IDH mutation, 1p/19q deletion, MGMT methylation, and survival time." (PMID 39431006, 2024). "We focused on PTBP1 because this RBP was already implicated in the regulation of alternative polyadenylation in glioblastomas and, more generally, in carcinogenesis via multitude of pathways." (PMID 39188787, 2024). "However, applying KAPAC to five normal and five glioblastoma tumor samples which showed most separable distributions of terminal exon lengths, we uncovered a pyrimidine motif, likely bound by PTBP1, as most significantly associated with changes in PAS use in these tumors." (PMID 29592812, 2018). "For example, the introduction of PTBP1‐baiting oligonucleotides into glioblastoma cells resulted in suppression of intracellular expression of multiple oncogenic protein isoforms, resulting in reduced cell proliferation, clone formation, and tumorigenicity." (PMID 40579921, 2025). "The multikinase inhibitor PT109 was found to suppress glioblastoma proliferation by indirectly reducing PTBP1 expression." (PMID 40790019, 2025). "Brain‐specific miR‐137 and muscle‐specific miR‐206 regulate PKM expression and inhibit the Warburg effect by directly binding PTBP1 mRNA in glioblastoma and rhabdomyosarcoma, respectively." (PMID 40579921, 2025). "In glioblastoma, PTBP1 functions as a splicing regulator by competitively binding to conserved sequences at multiple sites of BAF45d precursor mRNA." (PMID 40579921, 2025). "The Transwell assay showed that PTBP1 downregulation impaired the migration and invasion of glioblastoma cells." (PMID 39431006, 2024). "Ji claimed that PTBP1 was an important factor involved in the oncogenic function of the lncRNA LINREP in glioblastoma progression." (PMID 38071681, 2024). "The usage of many cassette exons alternatively spliced in glioblastomas are repressed at their 5′SS by the highly abundant PTBP1 RBP, whereas the usage of their 3′SS lacks splicing due to the lack of RBFOX RBPs." (PMID 38750024, 2024). "Next, PTBP1-silenced glioblastoma cells were constructed to evaluate the function of PTBP1 on glioblastoma migration and invasion." (PMID 39431006, 2024). "In our study, with the help of various bioinformatics and molecular biology experiments, we found that circ_0003137 regulated glioblastoma EMT via the PTBP1/PLOD3 signaling axis." (PMID 39431006, 2024). "Then, circ_0003137 promotes the EMT progression of glioblastoma cells by targeting the PTBP1/PLOD3 axis, accelerating the malignant progression of glioblastoma." (PMID 39431006, 2024). "Further, we carried out perturbation experiments (siRNA-mediated KD and overexpression of PTBP1) in two glioblastoma cell lines, U87MG and LN18." (PMID 39188787, 2024). "Nevertheless, applying MAPP to normal brain and glioblastoma samples, we uncovered many exons that appear to be coregulated by the PTBP1 and RBFOX RBPs, two regulators that were reported previously to act in concert." (PMID 38750024, 2024). "Another study reported that in glioblastoma, PTBP1 recognizes an alternative 5′ss within ubiquitin specific peptidase 5 (USP5) exon 15, resulting in the generation of USP5 isoform 2 with a shorter exon length." (PMID 37875914, 2023). "In glioblastoma, PTBP1 promotes glioblastoma progression by mediating annexin A7 exon splicing, eliminating its tumor suppressor functions." (PMID 36508323, 2023). "Another study indicated that lncRNA LINREP can promote glioblastoma progression through recruiting the formation of PTBP1/HUR complex." (PMID 36635762, 2023). "We detected PTBP1 protein expression in four glioblastoma cell lines and found that they were all PTBP1-abundant, with being slightly higher in U251 and KNS89 cells." (PMID 35664063, 2022).
glioblastoma (continued). "Lentiviral interference and inhibitors blocking tests demonstrated that UNC5B receptor and its downstream signaling were essential in the neural differentiation process mediated by PTBP1 knockdown in glioblastoma cells." (PMID 35664063, 2022). "The high TUJ1 and MAP2 positivity rates in M-cherry+ cells led us to conclude that knocking down PTBP1 alone can efficiently convert specific types of glioblastoma cells into a neural differentiation state." (PMID 35664063, 2022). "A DAPK1 inhibitor partially prevented the reprogramming of glioblastoma cells produced by PTBP1 knockdown, indicating the participation of UNC5B-DAPK1 pathway once again." (PMID 35664063, 2022). "We found that knocking down PTBP1 reprogramed glioblastoma cells like U251, U87, and KNS89 into a neural differentiation state, significantly slowing down their proliferation rate." (PMID 35664063, 2022). "Bioluminescence, immunohistofluorescence (IHF), and Kaplan-Meier survival analyses were utilized to demonstrate the in vivo reprogramming efficiency of PTBP1 knockdown in U87 murine glioblastoma model." (PMID 35664063, 2022). "qRT-PCR and Western blot analyses were utilized to detect changes in PTBP1 mRNA and protein levels in U251 glioblastoma cells three days post infection (dpi), with more than 95% infection efficiency." (PMID 35664063, 2022). "hnRNP A1, hnRNP A2, and hnRNP I (also known as PTBP1) are highly expressed in glioblastoma and regulate the alternative splicing of PKM to promote tumor cell proliferation." (PMID 32967226, 2020). "KAPAC analysis of TCGA data reveals pyrimidine-rich elements associated with the use of poly(A) sites in cancer and implicates the polypyrimidine tract-binding protein 1 (PTBP1) in the regulation of 3′ end processing in glioblastoma." (PMID 29592812, 2018). "Our findings are supported by previous observations that PTBP1 acts antagonistically to CSTF2, repressing PAS usage, and that increased PTBP1 expression, as we observed in glioblastoma tumors, promotes proliferation and migration in glioblastoma cell lines." (PMID 29592812, 2018). "In particular, our analysis points to polypyrimidine tract binding protein 1 as a regulator of poly(A) site choice in glioblastoma." (PMID 29592812, 2018). "Our data demonstrated that recurrent glioblastoma showed more DAPI-PTBP1 positive cells and a higher mean intensity value of PTBP1 signal compared to resections from second surgeries that showed only reactive gliosis." (PMID 28282372, 2017). "We found the total mRNA levels of EGFR and four EGFR transcripts were dramatically reduced after PTBP1 stable knockdown, which in agreement with previous study that PTBP1 stablized mRNA of EGFR by inhibiting ANXA7-mediated EGFR degradation in glioblastoma." (PMID 28404950, 2017). "In addition, we validated the regulation of APA in PRRC2B by PTBP1 in siRNA-knockdown and overexpression experiments followed by RNA-sequencing in two glioblastoma cell lines." (PMID 39188787, 2024). "Next, circ_0003117 promotes glioblastoma cell EMT by targeting the PTBP1/PLOD3 axis." (PMID 39431006, 2024). "Altogether, the migration and invasion of glioblastoma cells could be facilitated by circ_0003137 via the PTBP1/PLOD3 axis." (PMID 39431006, 2024). "The RIP-PCR assays showed that only PLOD3 could be enriched by PTBP1 in circ_0003137-overexpressed glioblastoma cells." (PMID 39431006, 2024). "PTBP1 expression was assessed in glioblastoma tissues and cell lines." (PMID 39431006, 2024). "PTBP1 was upregulated in glioblastoma tissues and cell lines." (PMID 39431006, 2024). "Then, circ_0003137 promotes the EMT of glioblastomas by targeting the PTBP1/PLOD3 axis." (PMID 39431006, 2024). "Furthermore, the relationship between PTBP1 expression and glioblastoma clinical features was evaluated based on TCGA and CCGA." (PMID 39431006, 2024).
glioblastoma (continued). "High PTBP2 expression was significantly associated with good survival of glioblastoma, rather than nephroblastoma, while high PTBP1 expression predicted unfavorable survival in both glioblastoma and nephroblastoma." (PMID 37040518, 2023). "To further explore the mechanism of PTBP1 knockdown to initiate reprogramming of glioblastoma cells, we isolated total RNA from sh-Luci infected U251 cells three days post infection (sh-Luci-3d) and sh-PTBP1 infected U251 cells three and seven days post infection (sh-PTBP1-3, 7d) for sequencing." (PMID 35664063, 2022). "PTBP1 is aberrantly elevated in glioblastomas and serves as a marker for glioblastoma progression." (PMID 30962446, 2019). "PTBP1 has recently been reported to play a significant role in glioblastoma cell proliferation." (PMID 21655185, 2011). "Therefore, we believe that neuronal reprogramming caused by PTBP1 knockdown greatly inhibited the proliferation of glioblastoma cells, not just the effect of PTBP1 knockdown itself." (PMID 35664063, 2022). "In glioblastoma, the N6-methyladenosine (m6A)-modified LINREP interacts with the PTBP1/HuR complex and protects PTBP1 from ubiquitin-mediated degradation, thereby promoting tumor progression and potentially serving as a novel therapeutic target." (PMID 39859408, 2025). "In a study on glioblastoma, MA unveiled inhibitory effects on GSK-3β and its downstream pathways, splicing factors, PTBP1, SF2/ASF, and hnRNPA1, as well as anti-apoptotic regulators." (PMID 39863145, 2025). "Mechanistically, circ_0003137 physically binds to polypyrimidine tract binding protein 1 (PTBP1), enhancing the stability of procollagen-lysine, 2-oxoglutarate 5-dioxygenase 3 (PLOD3) and promoting the EMT of glioblastoma cells." (PMID 39431006, 2024). "In glioblastomas, the splicing-activating RBFOX RBPs are downregulated, whereas the PTBP1 splicing repressor is highly expressed compared to normal brain tissue." (PMID 38750024, 2024). "This suggests that the PTBP1 and RBFOX-dependent splicing program active in glioblastomas relative to healthy brain tissues is indeed similar to the one active in cells from the VZ relative to the further differentiated cells residing in the CP." (PMID 38750024, 2024). "In this research, we found that PTBP1 knockdown promoted neural differentiation in U251, U87 and KNS89 human glioblastoma cells and significantly decreased their proliferation in vitro." (PMID 35664063, 2022). "Recent study featured sophisticated interplay of Ptbp1, Ptbp2, RbFox2, and SON (SON DNA and RNA binding protein) promoting glioblastoma multiforme (GBM) genesis." (PMID 35204777, 2022). "We found the PTBP1 expression was increased with WHO grade both in our cohort and CGGA/TCGA datasets, and the expression was highest in glioblastoma." (PMID 35299889, 2022). "Splicing factor PTBP1 is reported to promote oncogenic functions in glioblastoma (GBM)." (PMID 34548489, 2021). "Taken together, these findings demonstrate that SON overexpression in malignant gliomas, especially in GBM, has strong correlations with PTBP1 overexpression and PTBP2 downregulation, suggesting that there is a functional connectivity between SON, PTBP1, and PTBP2 in glioblastoma cells." (PMID 34548489, 2021). "The Transwell assay revealed that, when PTBP1 was absent, circ_0003137 overexpression did not affect the migration and invasion of glioblastoma cells." (PMID 39431006, 2024). "It is noteworthy to mention that inhibiting the expression of PTBP1 does not have an impact on the differentiation of glioblastoma cells, but contributes to the inhibition of cancer growth." (PMID 37808305, 2023). "Unfortunately, knocking down PTBP1 does not allow all types of glioblastoma cells to enter a neural differentiation stage." (PMID 35664063, 2022). "Here, we identify SON as a master regulator that activates PTBP1-mediated oncogenic splicing while suppressing RBFOX2-mediated non-oncogenic neuronal splicing in glioblastoma multiforme (GBM)." (PMID 34548489, 2021).
glioblastoma (continued). "In our study, NeuroD4 successfully reprogrammed U251 and KNS89 glioblastoma cell lines into a neural differentiation state, achieving an efficiency of over 90%, which is comparable to the reprogramming efficiency achieved by overexpressing ASCL1 or knocking down PTBP1." (PMID 37582760, 2023). "This indicates that differential PTBP1 expression is not the key to determine whether PTBP1 knockdown can reprogram glioblastoma cells." (PMID 35664063, 2022). "Similarly, the proliferation rate of infected LN229 glioblastoma cells did not alter significantly, demonstrating that PTBP1 knockdown cannot affect the fate of all glioblastoma cell lines." (PMID 35664063, 2022). "Similarly, circ_0003137 could not change the half-life of PLOD3 in PTBP1-deleted glioblastoma cells." (PMID 39431006, 2024). "Applying MAPP to GBM samples from two additional RNA-Seq cohorts recapitulated both the PTBP1 and RBFOX expression patterns and the CU-repeat and GCAUG k-mer activities, thereby confirming the PTBP1 and RBFOX RBPs as global regulators of the oncogenic splicing program acting in glioblastomas." (PMID 38750024, 2024). "In the field of oncology research, PT109, a novel multikinase inhibitor, reprogrammes glioblastoma multiforme (GBM) into oligodendrocytes by decreasing the level of PTBP1 and increasing the ratio of pyruvate kinase M1/2 (PKM1/2), and alters the metabolic pattern of GBM via the PTBP1/PKM1/2 pathway." (PMID 36635500, 2023).
colon carcinoma (25 papers, 2012 to 2025). "Colon cancer cells transient transfected with PTBP1 siRNA caused a significant decrease in cell viability compared with those transfected with the control siRNA." (PMID 28404950, 2017). "In colon cancer, miR‐1 and miR‐133b expression is downregulated, and overexpression of miR‐1 and miR‐133b binds PTBP1 mRNA to reduce PTBP1 expression and inhibit the Warburg effect." (PMID 40579921, 2025). "As one of the essential SFs for PKM, PTBP1 is highly expressed in two drug-resistant colon cancer cell lines (HCT-8/V and HCT116)." (PMID 38785973, 2024). "By performing RIP-qPCR assay in SW480 colon cancer cells, we found that PTBP1 indeed binds near this 3′ splice site, suggesting that PTBP1 directly represses Ptbp2 exon 10 inclusion in these cells." (PMID 36744439, 2023). "PTBP1 has been highlighted as an upregulated entity in colon cancer, while its increased expression in osteosarcoma is yet to be reported." (PMID 33621196, 2021). "The suppressed impacts of depleted PTBP1 is also confirmed to inhibit cell growth and proliferation in colon cancer." (PMID 33621196, 2021). "In order to show the effect of decreased PTBP1 expression levels in colon carcinoma cells in vivo, we synthetized an analogous recombinant adenovirus which encoded a PTBP1 shRNA or control shRNA." (PMID 28404950, 2017). "We also determined protein levels of PTBP1 in 6 different human colon cancer cell lines (HCT-116, SW480, HCT-8, HT-29, DLD1 and loVo), human normal colon epithelial cell lines (CCD 841 CoN) and human normal colon fibroblast cell line (CCD-112 CoN)." (PMID 28404950, 2017). "The results indicated that PTBP1 knock-down remarkably reduced the migratory and invasive ability of colon cancer cells." (PMID 28404950, 2017). "We already reported that the PKM-splicer PTBP1 acts as an oncogene in colon tumors to establish and maintain the cancer specific energy metabolism." (PMID 28106737, 2017). "Recently, we reported that miR-124 regulates the Warburg effect through targeting PTBP1 in colon cancer cells." (PMID 28380435, 2017). "By siRNA mediated knockdown PTBP1, we focused on the knockdown effect in three colon cancer cell lines including one from metastatic site (HCT-116, SW480 and loVo)." (PMID 28404950, 2017). "Gene silencing of PTBP1 in human colon cancer cell lines resulted in an increase in the PKM1/PKM2 ratio and induced apoptosis and/or autophagy of the targeted cells." (PMID 27513449, 2016). "Especially, we have investigated the effects of miRs that control PTBP1 expression in cancer cells, because we have found that most primary tumors including colon tumors samples show extreme overexpression of PTBP1." (PMID 26980745, 2016). "Similarly, apigenin downregulated PKM2 in colon cancer cells by inhibiting the Wnt/catenin pathway and reducing the synthesis of the splicing factor polypyrimidine tract-binding protein 1, resulting in decreased cell proliferation." (PMID 35706397, 2022). "It is suggest the possibility that the PTBP1 may paly an important role in transition of adenomas to colon carcinomas." (PMID 28404950, 2017). "Together, we supposed that PTBP1 may be a prognostic marker of stages II/III colon cancers and could be used to guide the invidually targeted therapy." (PMID 28404950, 2017). "Furthermore, PTBP1 regulates alternative splicing of many target genes involving in tumorgenesis in colon cancer cells." (PMID 28404950, 2017). "Also, miR-124 suppresses the Warburg effect through silencing PTBP1 or DEAD-box RNA helicase 6 (DDX6) in colon cancer cells." (PMID 26980745, 2016). "To clarify whether these anti-cancer effects induced by miR-1 and -133b depended on the binding to PTBP1, we examined the effects of knockdown of PTBP1 on colon cancer cells." (PMID 26980745, 2016). "Thus, the treatments knock down of PTBP1 exhibits growth ability in colon carcinoma cells." (PMID 28404950, 2017).
colon carcinoma (continued). "Our study indicated that knocking down PTBP1 or suppressing cortactin could both decrease cell migration and invasion in colon cancer cells and PTPB1 mediates inclusion of the alternative exon 11 in cortactin pre-RNA changing the F-actin binding domain involved in cell motility." (PMID 28404950, 2017). "MiR-339-5p has also been reported to inhibit glycolysis and colon cancer growth by reducing PKM2 expression through hnRNPA1 and PTBP1." (PMID 34782005, 2021). "For instance, in colon cancer, oncogenic Kirsten rat sarcoma viral (KRAS) activates the RAS–MAPK pathway, leading to an increase in the expression levels of the AS factor polypyrimidine tract-binding protein 1 (PTBP1), activated via transcription factor ELK1." (PMID 33261131, 2020). "In the case of human colon cancer DLD-1 cells, the combination treatment reduced the expression of c-Myc and PTBP1 at both mRNA and protein levels for a longer time than seen with the T24 or 253JB-V cells, which led to profoundly greater inhibition." (PMID 28106737, 2017). "In addition, kaempferol promotes miR-339-5p expression, which directly targets hnRNPA1 and PTBP1, reducing PKM2 expression and inhibiting glycolysis in colon cancer." (PMID 38785973, 2024). "Our data also supported the notion that over-expression of cortactin isoform-a could rescue the knocking down PTBP1 effect of migration and invasion in 3 colon cancer cell lines but not affect cell proliferation (data not shown)." (PMID 28404950, 2017). "Results from the analysis with the non-cancer multi-tissue network and the colon cancer GWAS included the genes KMT2B, PTBP1 and GEN1 (p-values 2.0 × 10− 6, 3.0 × 10− 6 and 3.0 × 10− 6, respectively)." (PMID 39010058, 2024).